IL6 (interleukin 6)
Diseases named in the same sentence as IL6 in open-access papers (continued):
Sharing a sentence is not in itself a finding about the gene and the disease.
infection (continued). "Finally, a number of studies have considered the utility of combined biomarkers, such as CRP with interleukin-6 (Il-6) in periprosthetic joint pathology showing superiority over other biomarkers (including procalcitonin) when distinguishing between aseptic joint loosening and infection [35•, 36]." (PMID 30225546, 2018). "CA16 infection also induced the release of LDH and IL-6, which were the marker of cell injury and caused cell apoptosis in cells." (PMID 30186868, 2018). "We showed that infection of pigs with an epidemic or endemic VSV induced disparate serum levels of IgM/IgG antibodies, systemic antiviral activity, TNF and IL-6 during the acute phase, as well as marked differences in virulence." (PMID 30158915, 2018). "IL-6 expression in retina increased and some microglial cells underwent apoptosis 4 h and 8 h after PVL infection, probably because of abnormal nitrotyrosine production in the retina." (PMID 29440661, 2018). "In contrast, the initial HAM response to infection displays a lag phase with few genes significantly up-regulated at the 2 h post-infection time point (CSF2, IL-1B, IL-6, IL-10, IL-21)." (PMID 29847580, 2018). "In spleen, mRNA expression of IL-1β, IL-6, IL-12, HMBG1, MCP-1, and TGF-β was significantly increased 20 h post-infection, while expression of M-CSF was significantly decreased." (PMID 29755322, 2018). "Levels of IL-6, IL-15, and MCP-1 were higher in response to DENV stimulation in subjects who experienced DF/DHF versus those with subclinical infections." (PMID 30557313, 2018). "A comparison between MPI cells and BMDM was also performed, showing that 8 h after infection with live bacteria, MPI cells were secreting more TNF-α, comparable amounts of IL-6 and less IL-1β than BMDM, at all the MOI tested." (PMID 29593716, 2018). "In this regard, it is interesting that previous data showed that in HIV patients there is an infection of Kupffer cells in the liver which enhanced LPS cell-surface receptors (TLR4) and increased IL-6 and TNF-a expression." (PMID 29434676, 2018). "UGB inhibited significantly MIF and IL-8 levels from 48 to 72 h after infection and UGL inhibited IL-6 (72 h) and IL-8 (48-72 h)." (PMID 28591408, 2017). "We identified IL-1β as a key cytokine capable of inducing IL-1β, IL-6, TNF-α, and trypsin in mouse lungs and human alveolar A549 cells in the early phase of infection." (PMID 27714503, 2017). "We did note reductions in both IL-6 and IL-17, and to a lesser extent TNFα in the BAL fluid of infected IL-36R-/- mice and IL-36γ-/- mice at 24 h post infection, as compared to WT mice." (PMID 29166668, 2017). "Preliminary studies reported that IL-6 and IFN-γ mRNA transcript levels increased during early stages of infection with CIAV." (PMID 29018431, 2017). "There was a significant decrease in the concentrations of TNF-α, IL-6, IL-8, and CCL2 present in the vaginal washes following the Us2 mutant infection compared with HSV-2 infected mice." (PMID 28827540, 2017). "BAFF, IL-6, RIG-1 and MDA5 were identified as differentially regulated genes following infection with attenuated or virulent strains in the kidney (P<0.05)." (PMID 28614378, 2017). "Our data indicate that PM1 induces low levels of proinflammatory cytokines IL-6, IL-8 and IL-1β, and the antimicrobial peptide HBD-2, but is able to stimulate, after only 6 h of infection, the expression of the anti-inflammatory cytokine TGF-β." (PMID 28212280, 2017). "In conclusion, BTV-8 infection induces an inflammatory response in the host characterized by increased IL-6, IL-12 and CXCL10 levels, but IL-1β levels only increased after the third infection." (PMID 28662714, 2017). "LPS-activated NF-κB in combination with LBP, and triggers the pro-inflammatory mediators of APR, such as IL-1β, IL-6 and TNF-α produced by macrophages or blood monocytes at the site of injury or infection." (PMID 28596485, 2017).
infection (continued). "In contrast, the IL-6 and TNF-α mRNA and protein levels following P. gingivalis infection were significantly reduced by the oral administration of LG2055 before infection." (PMID 28373699, 2017). "Third, influenza A virus (Hkx31; 105 PFU per mouse) infection in mice in vivo for 24 h resulted in greater increases in lung IFN-β, IL-1β, IL-6, and TNF-α mRNA, as well as serum and lung IFN-β protein in NOX2−/y mice." (PMID 28701733, 2017). "In patients and mice, EV-A71 infection enhances the expression of IL-1β, IFN-γ, and TNF-α, which can induce IL-6 expression." (PMID 29233145, 2017). "As early as 12 h post infection, peritoneal CD19(+) cells produce IFN-γ, IL-1β, IL-4, IL-6, IL-12, IL-17, IL-23, and TNF-α." (PMID 29085810, 2017). "The infection stimulated the release of TNF-α, IL-1β, IL-6, IL-8, and IL-10 production by infected cells." (PMID 29118740, 2017). "Of note, H. polygyrus infection promoted a long term up-regulation of IL-6 and CXCL1 expression in naïve mice which was still detectable 10 weeks after initial infection." (PMID 28938014, 2017). "In line with the severity of infection, the levels of TNF-α, IL-6, and IFN-γ were significantly higher in the Wt-immunized group than in the Δhfq-immunized group." (PMID 28727722, 2017). "Proinflammatory early response cytokines IL-6 and TNF-α were only detectable in a significant amount whenever infection was present." (PMID 29348965, 2017). "In the comparison of the levels of the cytokines, IL-6, IL-10, and CRP were statistically higher in patients with infection than the post-treatment values." (PMID 28148470, 2017). "Infection of BMDM and human macrophages with Mtb with esat-6 deletion induced diminished STAT3 activation and reduced IL-6 production compared to wild type and esat-6 complemented Mtb strains." (PMID 28106119, 2017). "In vivo, we found that that the expression levels of IL-2, IL-4, IL-6 and TNF-a in the lungs of H9N2 infected mice peaked on 2 days post-infection and then declined on days 4 and 6 post-infection." (PMID 28114957, 2017). "After 24 h of infection, cells infected with the Rv2029c-overexpressing BCG exhibited markedly higher expression of TNF-α and IL-6 than those infected with BCG or BCG-pMV261." (PMID 29204139, 2017). "The expression levels of IL-2, IL-4, IL-6 and TNF-α in calcitriol-treated infected mice were significantly lower than the untreated infected mice on 2 days post-infection (p <0.01)." (PMID 28114957, 2017). "The role of CMV-induced IL-6 in this process was confirmed by experiments demonstrating an increase in TER when cells were treated before and during infection with IL-6-neutralizing antibodies." (PMID 28241080, 2017). "Macrophages play important roles in host defense to infection, repair of damaged tissue, and secretion of pro-inflammatory cytokines such as TNF-α and IL-6 to modulate inflammatory response." (PMID 28397806, 2017). "Circulatory IFN-γ, IL-4, IL-5, IL-6 and TNF-α were increased in WT mice after infection with PcAS (respectively, p = 0.004, 0.004, 0.0081, 0.004 and 0.004)." (PMID 29062028, 2017). "P. gingivalis-infected mice produced higher amounts of IL-6 and TNF-α mRNA in the gingival tissues and GMCs, and higher protein levels in GMCs than those in sham-infected mice 1 day after the final infection." (PMID 28373699, 2017). "Ad-SOCS2 infection alleviated STZ-induced renal injury and pathological changes and inhibited STZ-induced IL-6, IL-1β and MCP-1 generation and activation of the TLR4/NF-κB pathway in DN rats." (PMID 29207635, 2017). "The expression of pro-inflammatory cytokines (TNF-α and IL-6) and chemokines (KC and MCP-1) was strongly reduced in the presence of LH-C from 4 to 6 days post infection." (PMID 28235408, 2017). "B. canis replication was confirmed in infected placental explants and the infection elicited an increased secretion of TNF-α, IL-8, IL-6 and RANTES." (PMID 29036184, 2017).
infection (continued). "In vitro experiments showed that siTIPE2 infection exacerbated the increased TNF-α and IL-6 concentrations, while Ad-TIPE2 infection reversed the increased TNF-α concentration in differentiated THP-1 cells under high glucose conditions (50 mmol/L)." (PMID 28626770, 2017). "Hepcidin levels increase homeostatically under high-iron conditions and in response to inflammation and infection via the BMP/SMAD and interleukin-6 (IL-6)/STAT3 pathways, respectively." (PMID 28893916, 2017). "After challenge with B. microti, the levels of cytokines including IL-17, IL-4, IL-6, IL-10, IL-12p70, G-CSF, IFN-γ, TNF-α, IL-2, GM-CSF, MCP-1, MIP-1α, MIP-1β, and MIP-2 in the serum of the BMSA vaccinated group changed as infection progressed." (PMID 29312230, 2017). "To achieve this, we evaluated the gene expression of pro-inflammatory (IL-1β and IL-6) and one anti-inflammatory cytokine (IL-10), as well as 2 chemokines (IL-8 and RANTES), in NaO-treated bMECs during infection." (PMID 28361042, 2017). "Elevated serum viremia at day 3 post infection correlated with a strong increase in the serum concentration of pro-inflammatory cytokines, including TNF-α, MCP-1, IP-10, IL-6 and KC." (PMID 28290449, 2017). "At 24 h after infection, the expression of cytokines and chemokines (i.e., TNF-α, IL-1β, IL-6, and IL-10) was evaluated by using ELISA." (PMID 28615695, 2017). "During infection, pro-inflammatory cytokines are released, specifically TNF, IL-1, IL-6 and IFN-g leading to increased expression of adhesion molecules on the surface of the vascular endothelium." (PMID 28202022, 2017). "Infected epithelial cells produced tumour necrosis factor-α (TNF-α) and IL-6 and the levels of these cytokines were significantly decreased in the presence of the P2X7R inhibitor implicating P2X7R in the production of infection-induced cytokines." (PMID 27559003, 2017). "Similar changes were observed with regard to expression levels of IL-6 and IFN-β in H9N2 infected A549 cells treated with calcitriol pre- or post- infection." (PMID 28114957, 2017). "There was a significant reduction in TNF-α, IL-6, and CXCL10 transcripts during Opal524R infection at this time point." (PMID 29138302, 2017). "Thirty days post infection, chitosan treatment resulted in MPO, MCP-1, TNF-α, IL-12p70 and IL-4 levels falling to control values, but IL-6, IL-10 and TGF-β were elevated." (PMID 29156562, 2017). "As expected, patients with infection had higher levels of blood leukocytes, CRP and plasma IL-6 levels." (PMID 28500294, 2017). "For A549 cells and MDM, the induction of IL-6 and CCL5 was greater during infection with NH1125B than NH1067B at both 18 and 24 hours post-infection." (PMID 28877226, 2017). "CSF concentrations of IL-10, IL-6, and IFN-γ were significantly increased in patients with late-stage infection, compared with those with early stage infection." (PMID 28927234, 2017). "The relative mRNA expression of interleukin (IL)-6, interferon (IFN)-γ, and lipopolysaccharide-induced tumor necrosis factor alpha factor (LITAF) over the course of the infection was evaluated using the qPCR method." (PMID 28659929, 2017). "We next measured pro-inflammatory mediators in splenic tissue by ELISA and observed significant increases in IL-6, CXCL1(KC), IFN-γ, TNF-α, CCL2 (MCP-1), and MMP-3 levels after infection." (PMID 28874800, 2017). "When severe clinical neurological signs appeared, the expressions of iNOS, IFNG, ILB, IL6, and IL8 genes were elevated dramatically in the brain following the very virulent plus (vv+) GaHV2 infection, especially at 10 and 14 dpi28." (PMID 28912500, 2017). "The expression levels of some ISGs (IFIT1, IFIT2, IFIT3) and proinflammatory cytokines (IL-6, IL-8) in DDX1-knockdown cells were analyzed after TGEV infection." (PMID 28848548, 2017).
infection (continued). "M2 markers were repressed whereas the M1 markers IL-6, TNF-α and IL-12 p40 were enhanced when C/EBPβ was knocked down prior to infection, suggesting that C/EBPβ regulates the M1/M2 balance in infected macrophages." (PMID 28558034, 2017). "The analysis of mRNA level of different cytokines revealed a different pattern of induction: IL-1β, IL-6, and IFN-γ are up-regulated in the antrum of mice at early time of infection, while CXCL5 and CXCL15 are induced only at 42 days." (PMID 29085807, 2017). "In serum, no changes in IL-1 concentrations and only slight increases in IL-6 and TNF-α were recorded within the first eight hours after infection, which is in accordance with results of previous studies." (PMID 28245826, 2017). "Despite the fact that measurements occurred two days after the initial infection, the alginate + LESB58 mice had significant increases in MCP-1, KC, IL-6, and TNF-α in the lungs and in KC and IL-6 in the serum." (PMID 29107983, 2017). "Based upon above observations, we postulate that the differentiation of mDC was activated following initial SFTSV infection, but quickly mitigated by high titers of virus and inflammatory cytokines such as TNF-α and IL-6." (PMID 28747721, 2017). "Only less than 4% of BMDMs expressed viral NP, indicative of productive infection with IAV, at 48 h p.i. in either WT or IL-6−/− mice, suggesting low infectability of mouse BMDMs with IAV." (PMID 28262742, 2017). "The expression of MAPK family genes, dual specificity phosphatases (DUSP) family members, TNF, IL-1, IL-6, JUN and NF-κB family genes were upregulated at early stage of infection in all the tissues indicated triggering of MAPK pathway." (PMID 28704394, 2017). "After infection, NK1.1+ cell depleted-mice exhibited significantly reduced levels of the cytokines IL-6, IL-12p40, and G-CSF, and of the chemokines CCL2 and CCL5 compared to mock-treated infected mice (P < 0.05)." (PMID 28706510, 2017). "Type I IFNs, IFN-γ, and pro-inflammatory cytokines, such as interleukin (IL)-1, IL-6, IL-8, IL-12, and tumor necrosis factor-alpha (TNF-α), have been shown to be upregulated in lung tissue and lung lavage after experimental infection of pigs with Swine IV." (PMID 28484702, 2017). "We found that LPS priming of macrophages immediately prior to infection with PE_PGRS41 expressing M. smegmatis, enhances TNF-α, IL-1β and IL-6 mRNA levels and secretion." (PMID 28440335, 2017). "siTIPE2 infection exacerbated the increased TNF-α and IL-6 concentrations, while Ad-TIPE2 infection reversed the increased TNF-α concentration in differentiated THP-1 cells under high glucose conditions (50 mmol/L)." (PMID 28626770, 2017). "IL-6 expression was also induced in HRSV, Makona and Ecran infection of A549 cells and in Ecran infection of A549 NPro cells." (PMID 28240256, 2017). "The notable findings in the present study were the early peak in both IL-6 and TNF-α levels, the high inflammatory cell infiltration in BAL fluids, and the severe pulmonary inflammation at 3 days post-infection in asthmatic/A(H1N1)pdm09 mice." (PMID 28831046, 2017). "Despite diminished levels of tumour-necrosis factor (TNF), IL-1β, IL-6, IL-12, IL-18 and MCP-1, and decreased neutrophil recruitment to the infection site, resistance to pulmonary tularaemia is increased." (PMID 28580947, 2017). "In each case, IL-6 and CCL5 induction was greater during infection with NH1125B than NH1067B (respectively) indicating that there are likely viral-specific factors involved in the degree of cytokine and chemokine induction during infection." (PMID 28877226, 2017). "IFNg, IL6, KC (CXCL1) and LIX (CXCL5) were higher in the lungs of CB infected mice, indicating a heightened proinflammatory response in the CB infection." (PMID 28155887, 2017).
infection (continued). "In response to infection with hRSV, human AEC-derived cell lines secrete cytokines and chemokines in vitro, including IL-6, IL-8, CCL2, CCL3, and CCL5 that promote the recruitment of monocytes and eosinophils to the site of infection." (PMID 29230219, 2017). "Similar to norovirus challenge infections, the natural infection reported here transiently increased serum IFN-γ, IL-2, IL-6 and TNF-α concentrations." (PMID 28815218, 2017). "IL-6 mRNA levels were then measured by RT-qPCR after super-infection with IV H1N1(M) and S. aureus 6850 and compared with IL-6 mRNA levels after treatment with solvent control." (PMID 28195157, 2017). "The cytokine cascade events following B. pseudomallei infection has been studied in several animal models and show an up regulated mRNA expression of inflammatory cytokines such as IL6, IL12, IL10, IFNγ, TNFα and IL1β within 72 hours of infection." (PMID 28628607, 2017). "MCs also produce a wide variety of soluble mediators potentially relevant to mycobacterial immunity, including IL-13, IL-12, IL-6, IL-4, TNF-α, CCL5, CXCL2, CCL7, and CCL2, following infection with Streptococcus equi." (PMID 29089945, 2017). "Abrogation of NLRP10 expression in epithelial cells reduced IL-8 and IL-6 release due to diminished activation of p38 MAPK, as well as NF-κB–RelA/p65 activity upon HeLa cell infection with S. flexneri." (PMID 29163529, 2017). "The pro-inflammatory mediators (TNF and IL-6) MHC-I/II and B7.2 (CD86) were also up-regulated during infection over time." (PMID 28067803, 2017). "siTIPE2 infection exacerbated the increased TNF-α and IL-6 concentrations in differentiated THP-1 cells under high glucose conditions (50 mmol/L), while infection with TIPE2 adenovirus reversed the increased TNF-α concentration." (PMID 28626770, 2017). "Together this data showed that IL-6 was produced rapidly upon RSV infection, both locally and systemically, and remained detectable throughout the course of infection." (PMID 28953978, 2017). "This experimental approach recapitulates what occurs in patients with systemic JIA: an infection triggers MAS on a background of active disease, which is indeed characterized by high levels of IL-6." (PMID 28095869, 2017). "Therefore, when DC (or macrophages) are confronted with non-invasive yeast, they can clear the infection by rapid phagocytosis, especially macrophages, and limited production of IL-1β, and hence in the case of mDC, which respond to autocrine and macrophage-derived IL-1β IL-6 and IL-23." (PMID 28736555, 2017). "We therefore collected serum samples after infecting mice with of E. coli (2×108 CFU) by i.p. injection; serum was collected 1, 2.5, and 6 h after infection for measuring TNF-α, IL-6 and IFN-γ levels, respectively." (PMID 28815056, 2017). "Most inflammatory markers, such as interleukin-6 (IL-6), tumor necrosis factor-α (TNF-α), CRP, and fibrinogen, increased significantly in response to infection and in active diseases states." (PMID 28539965, 2017). ", 2005), interleukin (IL)‐1α, IL‐6, tumor necrosis factor (TNF)‐α, and interferon (IFN)‐γ levels were significantly upregulated upon infection of ND mice, as were many others." (PMID 27794208, 2017). "Antigenicity studies using PvDBPII universal epitopes have shown that lymphoproliferation, IL-6, and IFN-γ production is induced in peripheral blood mononuclear cells (PBMCs) from individuals exposed to infection." (PMID 28243235, 2017). "Consistent with our in vivo results, there was increased cytokine and chemokine production, with elevated IL-6, G-CSF, MCP-1, MIP-1α and RANTES at 24 h post-infection (MOI 5)." (PMID 28195529, 2017). "We found a significant increase in levels of IFN-α and IFN-β, interferon-stimulated genes (ISGs) CXCL-10 and ISG15, and the proinflammatory cytokines interleukin-6 (IL-6) and tumor necrosis factor (TNF) at 16 to 24 hpi following infection with N1040A." (PMID 27965448, 2016).